IL13 (interleukin 13)
Diseases named in the same sentence as IL13 in open-access papers (continued):
Sharing a sentence is not in itself a finding about the gene and the disease.
inflammatory skin disease (12 papers, 2014 to 2025). Inflammatory skin disorders covers a broad category that includes many conditions ranging in severity, from mild itching to grave medical health complications These disorders are common in people of all ages and races. "ACD is an inflammatory skin disease, driven by a complicated cell-cell network mediated by several T cell-associated cytokines, including Th1 cytokine IFNγ, Th2 cytokines IL4, IL13, and Th17 cytokine IL17." (PMID 39213029, 2024). "The inflammatory skin disease is characterized by cutaneous hyperreactivity to allergens and by a microenvironment in the skin enriched with Th2 cytokines, such as IL-4 and IL-13, and histamine released from activated immune cells." (PMID 34769080, 2021). "T helper 2 (Th2)-mediated dermatoses are inflammatory skin diseases driven by CD4+ Th2 cells that produce interleukin (IL)-4, IL-5, IL-13, and IL-31, promoting immunoglobulin E (IgE) class switching, eosinophil recruitment, mast cell degranulation, and pruritus." (PMID 41226755, 2025).
polyp (12 papers, 2014 to 2025). A usually exophytic mass attached to the underlying tissue by a broad base or a thin stalk. "Both IL-5 and IL-13 are elevated in polyp sinonasal tissue extracts compared with controls, and IL-5 immunoreactivity was previously found to be restricted to MCTs in asthmatic bronchial mucosal biopsies." (PMID 39744949, 2025). "T helper type 2 releasing cytokines, interleukins (IL-5 and IL-13), as well as histamine, are frequently found in high concentrations in polyp tissue." (PMID 37605661, 2023). "Signature Th1 (IFN-γ), Th2 (IL-5 and IL-13), and Th17 (IL-17A) cytokines were measured in iNKT cells from four inflammatory subtypes of polyp tissues." (PMID 35720287, 2022). "Cytokines such as IL-4 and IL-13 released during immune activation may promote mucosal hyperplasia, accelerating polyp formation and recurrence." (PMID 40606441, 2025). "However, when we attempted to evaluate the importance of IL-13 in MUC5AC production and glandular hyperplasia, we only observed very low levels of IL-13 in these polyp tissues and we failed to establish association between IL-13 and MUC5AC expression in this cohort (data not shown)." (PMID 24892823, 2014).
pulmonary edema (12 papers, 2012 to 2024). Accumulation of fluid in the lung tissues causing disturbance of the gas exchange that may lead to respiratory failure. "IL-4 and IL-13 have been detected at high concentrations in patients with virus-associated pulmonary edema, further supporting their role in conditions with pulmonary hypersecretion." (PMID 39052685, 2024). "In a male neonate with pulmonary edema, the cytokines IL-6, IL-8, IL-10, IL-13, IL-17, and IFN-γ rises sharply during the first few hours after birth and then decreases significantly." (PMID 35725416, 2022). "IL-6 and IL-13 levels are remarkably higher in patients with CNS infections and pulmonary edema with fatal outcomes than in uncomplicated patients." (PMID 29156632, 2017). "We hypothesized that IL-33 treatment may act through ILC2s to stimulate IL-13 production, leading to acute lung injury, vascular permeability, and resulting pulmonary edema." (PMID 33974563, 2021). "More significantly, IL-13 levels were consistently elevated in the pulmonary edema group, which considered that IL-13 might contribute to the pathogenesis of PE." (PMID 32089650, 2020).
Sjögren’s syndrome (12 papers, 2014 to 2023). "The lympho-myeloid pathotype of RA frequently includes the formation of organised ectopic lymphoid-like structures (ELS), and the formation of ELS in Sjögren’s syndrome has been shown to be dependent on IL-13 signalling." (PMID 33066816, 2020). "The lacrimal gland (LG) of the CD25-/- model of Sjögren’s syndrome (SS) has high interleukin (IL)-17, IL-13 and interferon-gamma (IFN-γ) cytokines." (PMID 25889094, 2015). "The study aimed to quantify certain cytokines involved in the pathomechanism of primary Sjögren syndrome (IL2, IL5, IL6, IL10, IL13, TNFα, IFNγ) and determine their common clinical correlation." (PMID 36143051, 2022). "In the proinflammatory group patients with Sjogren's syndrome (SS) and patients with SSc had increased levels of IL-13, patients with SLE had significantly increased levels of IFN-γ and significantly decreased levels of IL-13 and patients with RA had significantly increased levels of IL-8." (PMID 35860745, 2022).
Alzheimer disease (11 papers, 2014 to 2026). A progressive, neurodegenerative disease characterized by loss of function and death of nerve cells in several areas of the brain leading to loss of cognitive function such as memory and language. "In controls, cortical perfusion declined with increasing IFN-γ, IL-2, IL-4, IL-6, IL-10, IL-12p70, IL-13 and tumour necrosis factor-α (TNF-α) but these relationships were lost with progression of Alzheimer’s disease, and with infection (even in Braak stage 0–II brains)." (PMID 33723589, 2021). "Intracerebral microinjection of a mixture of IL-4 and IL-13 effectively restored spatial memory and learning abilities in C57BL/6 mice with overexpression of the amyloid-protein precursor 23 gene (AβPP23) (Alzheimer’s disease) through the increase of the IL-4 content in the hippocampus." (PMID 32778140, 2020). "Except for IL-6 and IL-13, brain cytokine level was not related to possession of APOE ε4 in either controls or Alzheimer’s disease brains (Supplementary)." (PMID 33723589, 2021).
coronary artery disease (11 papers, 2016 to 2025). "Similarly, another study showed decreased IL-13 levels in patients with coronary artery disease subjects." (PMID 30674322, 2019). "In addition to elevation of the proinflammatory cytokines IL1β, TNF-α and IL-6, exercise may reduce C-reactive proteins in patients with coronary arteriosclerosis and Type II T helper cytokines (IL-5 and IL-13) in asthmatic BALB/c mice." (PMID 32778140, 2020).
hepatocellular carcinoma (11 papers, 2009 to 2025). A malignant tumor that arises from hepatocytes. "A recent cohort study found that patients who developed hepatocellular carcinoma despite maintaining a sustained virological response against hepatitis C virus were linked to increased circulating levels of IL13." (PMID 34235145, 2021). "Transwell and MTT assays demonstrated that the proliferation, migration, and invasion capabilities of liver carcinoma cells were augmented by IL‐4 and IL‐13 contrasted with the DMSO control group, whereas PLX3397 weakened these abilities." (PMID 39268355, 2024). "These patients were matched to controls who did not develop hepatocellular carcinoma, and IL13 was found to be the only strong factor associated with its development." (PMID 34235145, 2021). "Inhibiting the expression of HSP70 blocks the secretion of IL-13 in ILC2 cells, leading to the suppression of hepatocellular carcinoma (HCC) progression." (PMID 38203352, 2023). "Lan T also reported that in hepatocellular carcinoma KIAA1429 controls the differentiation of T helper 2 (Th2) by inducing separation of RNA binding protein HuR, and so affects the expression of IL-4, IL-5, and IL-13." (PMID 35095993, 2021).
osteoarthritis (11 papers, 2011 to 2025). A noninflammatory degenerative joint disease occurring chiefly in older persons, characterized by degeneration of the articular cartilage, hypertrophy of bone at the margins and changes in the synovial membrane. "ACS is another blood derivative that contains various types of cytokines, especially anti-inflammatory cytokines such as IL-1Ra and IL-13 and is used to inhibit inflammation in injuries such as osteoarthritis." (PMID 40896180, 2025). "It was reported that avocado and soybean unsaponifiables can restrain osteoarthritis through inhibition of proinflammatory cytokines such as IL-1β, IL-3, IL-6, IL-8, IL-13, and TGF-β; also, they can modulate oxidative damages by repression of ROS production." (PMID 34258301, 2021). "The intraperitoneal administration of IL-13 induces marked analgesia in an inflammatory model of osteoarthritis and peritonitis, which confirms its anti-inflammatory properties." (PMID 32185190, 2020). "Ingenuity pathway analysis of male VICs with UTY-KD on blank and PS-NP gels showed strong associations to pathways related to osteoblasts and chondrocytes in inflammatory diseases, osteoarthritis signaling, and interleukin-4, interleukin-13, and interleukin-17 signaling, among others." (PMID 40073144, 2025). "Furthermore, in osteoarthritis synovial cells, IL-13 activated signal transducer and activator of transcription 6 (STAT6) to upregulate POSTN expression." (PMID 38020106, 2023). "For example, the serum levels of inflammatory cytokines, including IL-6, IL-13, and TNF-α, were significantly elevated in patients with osteoarthritis secondary to meniscus injury." (PMID 39330256, 2024). "As reported in this recent work, the pre-treatment with RPH had a suppressive effect on the mediators that contributed to the progression of osteoarthritis by inhibiting collagen 2, COX-1-2, MMP-13, TNF-α, and IL-13 expression." (PMID 32340224, 2020).
scleroderma (11 papers, 2012 to 2025). Scleroderma is a rare autoimmune connective tissue disorder characterized by abnormal hardening of the skin and, sometimes, other organs. "Systemic inflammation and increased inflammatory markers such as IL-4 and IL-13 are associated with scleroderma." (PMID 28540270, 2017). "IL-13 and its receptor expression levels are elevated in a murine model of bleomycin-induced scleroderma." (PMID 36136606, 2022). "We have previously characterized that expression of several IL13 target genes correlates with the induction and severity of fibrotic skin diseases such as scleroderma." (PMID 22957096, 2012). "Additionally, these cells also express IL13Ra1, which is upregulated in GVHD, suggesting both that they are competent to respond to IL13, and increased IL13Ra1 was associated with an IL13-driven expression signature in murine GVHD and human scleroderma." (PMID 22957096, 2012). "Interestingly, IL-13 overexpression induces experiment rodent PH, and plasma IL-13 is elevated in scleroderma-associated PAH as compared toscleroderma without PAH, suggesting a plausible role for type 2inflammation in PAH more generally." (PMID 36875282, 2022). "IL-6, IL-13, IL-17, and TNF-α are cytokines recognized to be involved in the pathophysiology of scleroderma." (PMID 34445632, 2021). "Especially IL-13, produced by CD8+CD28− scleroderma T cells, enhances COL1A1 protein expression in dermal fibroblasts." (PMID 29033951, 2017). "Additionally, EGR1 is aberrantly expressed in animal models such as transgenic mice expressing TGF-ß or IL-13 and human fibrotic diseases such as IPF and scleroderma." (PMID 39944354, 2024). "Additionally, we have previously observed that expression of IL13Ra1 correlated with an IL13 response signature in both a mouse model of sclerodermatous GVHD and in human scleroderma." (PMID 22957096, 2012). "The neutralizing antibody SAR156597 for IL-4 and IL-13, which directly induce CCL17, reduced the CCL17 levels in the plasma and exhibited significant improvement in the skin scores and a trend toward improved respiratory function in a phase II study of the multiorgan fibrosing disease scleroderma." (PMID 40269953, 2025).
steatosis (11 papers, 2014 to 2024). Increased lipid within the cytoplasm of cells. "Studies using the NAFLD model also highlighted the importance of IL-13 in the liver by showing that IL-13 was involved in progression from simple steatosis to metabolic-disfunction-associated steatohepatitis." (PMID 39200991, 2024). "IL-13 is involved in the processes contributing to the transition from metabolic-dysfunction-associated steatosis to MASH." (PMID 37629063, 2023). "Most of the measured cytokines had similar concentrations, except for IL-9, IL-10, IL-13 and IL-22, which were significantly lower in patients with steatosis." (PMID 39200991, 2024). "Activated IL-17-secreting NKT cells were dominant in liver during the beginning of the steatosis phase, whereas IL-4/IL-13-secreting iNKT cells were prevalent later in the disease." (PMID 34440206, 2021). "Moreover, IL13 is shown to activate ductular reaction, steatosis, and fibrosis." (PMID 36881564, 2023). "Furthermore, IL-13-regulated lipogenesis, bile acid synthesis, and biliary-dependent steatosis seem to be distinct cellular pathways from fibrosis, suggesting the possible intervention of IL-13 for the promotion of hepatobiliary expansion without aggravating fibrosis." (PMID 32676074, 2020). "During weeks 1 to 4, we noticed an upregulation of low‐grade chronic inflammatory cytokines (IL‐6 and IL‐13) and inflammatory chemokines (MIP‐1α and eotaxin), which concurred with the onset of steatosis." (PMID 38952069, 2024). "In this study, we focused on the role of IL-22, IL-9, IL-10 and IL-13 in CHC, particularly in the context of steatosis." (PMID 39200991, 2024).
acute promyelocytic leukemia (10 papers, 2019 to 2025). An aggressive form of acute myeloid leukemia (AML), characterized by arrest of leukocyte differentiation at the promyelocyte stage, due to a specific chromosomal translocation t(15;17) in myeloid cells. "In acute promyelocytic leukemia (APL), IL-13-producing ILC2s participate in the establishment of a pro-tumor microenvironment by activating monocytic myeloid-derived suppressor cells (M-MDSCs)." (PMID 39858045, 2025). "In patients who are in remission from acute promyelocytic leukemia (APL), there is a decrease in ILC2s, IL-13, prostaglandin D2 (PGD2), and MDSCs." (PMID 40497988, 2025). "In patients with acute promyelocytic leukemia (APL), tumor-activated intrinsic lymphocytes (ILC2) secrete IL-13 to induce M-MDSC production and support tumor growth, whereas all-trans retinoic acid (ATRA) treatment reverses the ILC2-induced increase in MDSCs." (PMID 35854339, 2022). "A similar observation has been made in acute promyelocytic leukemia (APL), a subset of AML in which tumor-derived PGD2 and NKp30-BH76 engagement activates ILC2s to secrete IL-13 that stimulates myeloid-derived suppressor cells (MDSC)." (PMID 33477248, 2021). "In acute promyelocytic leukemia (APL) patients, tumor-activated ILC2s secreted IL-13 to induce M-MDSCs (CD33+CD14+HLA-DR-) and to support tumor growth, while ATRA treatment reversed the increase of ILC2-MDSCs in APL." (PMID 31640764, 2019). "In acute promyelocytic leukemia (APL) patients, peripheral ‘group 2 innate lymphoid cells’ (ILC2s) were found to be increased and hyperactivated, and in turn activated M-MDSC (CD14+CD33+) through IL-13 secretion." (PMID 36304465, 2022). "As for patients with acute promyelocytic leukemia (APL), specifically impairing the immunosuppressive axis PGD2/IL-13/NKp30 can partially decrease the numbers of ILC2s and M-MDSC to ameliorate survival." (PMID 31354745, 2019).
allergic conjunctivitis (10 papers, 2011 to 2024). "Overexpression of IL-13 is linked to the development of pathophysiological features consistent with allergic conjunctivitis including the hyperplasia of goblet cells in the epithelial layer of the conjunctiva." (PMID 38541674, 2024). "It is of note that mucoid discharge does occur in allergic conjunctivitis due to IL-13-induced hypersecretion of mucin from activated goblet cells." (PMID 38541674, 2024). "TSLP can activate mast cells to secrete IL-13, a cytokine that plays a pathophysiological role in allergic conjunctivitis." (PMID 38541674, 2024). "As such, monoclonal antibody against IL-4R alpha can attenuate the IL-4 and IL-13-induced pathophysiological changes in allergic conjunctivitis." (PMID 38541674, 2024). "The development of an ophthalmic-formulated version of this drug will serve to eliminate or minimize the involvement of IL-4 and IL-13 in mediating type 2 inflammatory processes in allergic conjunctivitis." (PMID 38541674, 2024). "This would be in line with a role for periostin (and IL-13) in mucosal immunity as suggested by the presence of excess periostin and IL-13, in tear fluid from patients with severe allergic conjunctivitis." (PMID 36763690, 2023). "Several reports have shown that, following activation of Janus-kinases (JAKs) in allergic conjunctivitis, IL-4 and IL-13 induce the expression of specific genes by activating STATs." (PMID 37784129, 2023). "Immunohistochemical staining confirmed an increase in TSLP, IL-4, IL-5, and IL-13 production in the eyes with various types of allergic conjunctivitis." (PMID 27504196, 2016). "The tear TSLP, IL-4, IL-5, and IL-13 expression levels in different types of allergic conjunctivitis were found elevated to varying degrees in the VKC, SAC, and PAC compared with the control group; the differences were statistically significant (P < 0.001)." (PMID 27504196, 2016). "Immunohistochemistry, real-time PCR, and Luminex technology were used to measure the expression of TSLP, IL-4, IL-5, and IL-13 in the tears and conjunctival cell of the normal population and patients with three types of allergic conjunctivitis." (PMID 27504196, 2016). "The present study sought to investigate the expression of TSLP and its downstream molecules IL-4, IL-13, and IL-5 in the conjunctival tissue of patients with allergic conjunctivitis and tear." (PMID 27504196, 2016). "Also, there was a significantly higher value of total IgE IU/ml, IL13 Pg/ml value in severe allergic conjunctivitis compared to moderate/mild allergic conjunctivitis." (PMID 39386093, 2024). "The purpose of this study is to determine whether IL4, IL5 and IL13, players in allergic conjunctivitis, directly regulate mucin production in rat conjunctival goblet cells." (PMID 30111832, 2018). "In light of our results, the high levels of IL4, IL5, and IL13 that characterize allergic conjunctivitis could be the reason for the increased number of goblet cells and could have a role in the mucin overproduction found in this pathological condition." (PMID 30111832, 2018). "We conclude that the high levels of IL4, IL5, and IL13 that characterize allergic conjunctivitis could be the reason for higher numbers of goblet cells and mucin overproduction found in this condition." (PMID 30111832, 2018). "A study reported increases in IL-1β, IL-2, IL-5, IL-6, IL-12, IL-13, in seasonal allergic conjunctivitis (SAC), vernal keratoconjunctivitis (VKC) and atopic keratoconjunctivitis (AKC), while IL-4, IFN-γ and IL-10 levels were increased in SAC and VKC compared to controls." (PMID 21298010, 2011). "The conjunctival tissues of various types of allergic conjunctivitis displayed stronger TSLP, IL-4, IL-5, and IL-13 staining throughout the entire epithelium than did those of normal controls." (PMID 27504196, 2016).
allergic conjunctivitis (continued). "Tanaka and Alfonso demonstrated that Sema3a suppressed the release of Th2-related cytokines (IL-5, IL-13 and IL-4) and inflammatory cytokines (IFN-α, IL-17 and TNF-α) but increased levels of the cytokine IL-10 in experimental allergic conjunctivitis and autoimmune arthritis models." (PMID 29975739, 2018).